DCP1A (decapping mRNA 1A)
Description:
Necessary for the degradation of mRNAs, both in normal mRNA turnover and in nonsense-mediated mRNA decay. Removes the 7-methyl guanine cap structure from mRNA molecules, yielding a 5'-phosphorylated mRNA fragment and 7m-GDP. Contributes to the transactivation of target genes after stimulation by TGFB1. Essential for embryonic development.
Synonyms: SMIF; HSA275986; SMAD4IP1; Nbla00360
Tractability: PROTAC: ubiquitination databases record sites on it; its protein half-life has been measured.
Gene: Protein-coding gene on chromosome 3 (53,283,429 to 53,347,683, reverse strand). Ensembl gene ENSG00000272886.
Subcellular location: Cytoplasm, P-body; Nucleus
Subcellular location (Human Protein Atlas): Cytoplasmic bodies
Pathways (Reactome):
Metabolism of RNA: Butyrate Response Factor 1 (BRF1) binds and destabilizes mRNA; Nonsense Mediated Decay (NMD) enhanced by the Exon Junction Complex (EJC); Tristetraprolin (TTP, ZFP36) binds and destabilizes mRNA; mRNA decay by 5' to 3' exoribonuclease
Gene Ontology:
Molecular function: 5'-(N(7)-methylguanosine 5'-triphospho)-[mRNA] hydrolase activity; identical protein binding; protein binding; mRNA binding; enzyme activator activity; kinesin binding
Biological process: mRNA methylguanosine-cap decapping; protein localization to cytoplasmic stress granule; deadenylation-dependent decapping of nuclear-transcribed mRNA; nuclear-transcribed mRNA catabolic process, deadenylation-dependent decay
Cellular component: cytoplasm; cytoplasmic ribonucleoprotein granule; membrane; nucleus; cytosol; P-body; dendrite
Genetic constraint (gnomAD): Loss-of-function variants: 10 observed, 41.02 expected, observed/expected ratio (o/e) 0.24, 90% interval 0.15 to 0.41. The upper end of that interval is the gene's LOEUF score, 0.41, which puts it in group 1 of 6, group 1 being the genes least tolerant of losing a copy. Missense variants: 541 observed, 625.46 expected, observed/expected ratio (o/e) 0.86, 90% interval 0.81 to 0.93. Synonymous variants: 246 observed, 250.81 expected, observed/expected ratio (o/e) 0.98, 90% interval 0.88 to 1.09.
Homologues: Orthologues: chimpanzee DCP1A (99% identical), macaque DCP1A (98% identical), dog DCP1A (91% identical), guinea pig DCP1A (90% identical), rabbit DCP1A (90% identical), mouse Dcp1a (89% identical), rat Dcp1a (88% identical), pig DCP1A (87% identical), tropical clawed frog dcp1a (46% identical), zebrafish dcp1a (34% identical), Drosophila melanogaster DCP1 (18% identical), Caenorhabditis elegans dcap-1 (11% identical). Paralogues in human: DCP1B (31% identical).